NRG1 (neuregulin 1)
Diseases named in the same sentence as NRG1 in open-access papers (continued):
Sharing a sentence is not in itself a finding about the gene and the disease.
lung cancer (46 papers, 2016 to 2026). A malignant neoplasm involving the lung. "Kaplan-Meier analysis of survival indicated that high level of NRG1 was significantly associated with poor survival rate of lung cancer patients." (PMID 40959099, 2025). "In lung cancer specifically, several NRG1 fusion partners, including CD74, ATP1B1, SLC3A2, SDC4, RBPMS, and WRN, have been identified." (PMID 40730881, 2025). "In the present study, we demonstrated that lung cancer derived-CAFs possessed a high level of NRG1, and CAFs-secreted NRG1 mediated the effect of CAFs on resistance of lung cancer cell to osimertinib." (PMID 40959099, 2025). "We then compared the expression of NRG1 among fibroblasts, lung cancer cells and normal lung bronchial epithelial cells." (PMID 40959099, 2025). "Expression of NRG1 was shown to be downregulated in lung cancers; addition of exogenous NRG1 reduced cancer cell proliferation and migration, while its downregulation by siRNA promoted cell growth, migration, and invasion potential." (PMID 41439026, 2025). "Aims to characterize NRG1 fusion-positive lung cancers in the largest and most diverse series to date." (PMID 40641929, 2025). "“Advanced, unresectable, or metastatic non–small cell lung cancer (NSCLC) harbouring a neuregulin 1 (NRG1) gene fusion with disease progression on or after prior systemic therapy." (PMID 40265416, 2025). "Our finding suggests the potential value of CAFs-derived NRG1 as a novel therapeutic target for osimertinib resistance in lung cancer." (PMID 40959099, 2025). "In summary, we demonstrated that CAFs promotes osimertinib resistance of lung cancer cells via NRG1-mediated activation of HER3/AKT/NF-κB signaling pathway." (PMID 40959099, 2025). "By applying rhNRG1 and NRG1 neutralizing antibody, both sphere formation assay and stemness-related gene examination revealed that CAFs facilitated lung cancer cell stemness under osimertinib treatment via NRG1." (PMID 40959099, 2025). "In 2024, it was approved by the FDA for metastatic NRG1 fusion-positive solid tumors, especially for pancreatic and lung cancer after failure of standard of care." (PMID 40332427, 2025). "The NRG1 fusion type of lung cancer displays worse outcomes due to its resemblance to cancer stem cells and its resistance against both chemoimmunotherapy strategies." (PMID 40332427, 2025). "A total of 36 NRG1 fusion events were identified in 12,458 lung cancer patients, reflecting a frequency of 0.29% within this group." (PMID 40730881, 2025). "A large multicenter clinical trial, eNRGy1, demonstrated that patients with lung cancer who exhibit an NRG1 fusion with low PD-L1 expression (28%) and low TMB demonstrate a reduced response to immunotherapy." (PMID 40730881, 2025). "Our finding highlights the potential value of CAFs-derived NRG1 as a novel therapeutic target for osimertinib resistance in lung cancer." (PMID 40959099, 2025). "qPCR results showed that NRG1 level in fibroblasts is higher than that in lung cancer cells and normal lung bronchial epithelial cells, and CAFs possess higher level than NFs." (PMID 40959099, 2025). "Knockdown of NRG1 in CAFs significantly mitigated the promoting effect of CAFs on lung cancer cell growth." (PMID 40959099, 2025). "The eNRGy trial, a global multi-center phase I/II clinical trial for NRG1 fusion-positive cancers, including lung cancer, has been initiated (NCT02912949)." (PMID 38957319, 2024). "This promising outcome suggests that Zeno holds potential as a targeted therapy for NRG1 fusion-positive lung cancer." (PMID 38957319, 2024). "A multi-center alliance study compiling data from the management of NRG1 fusion-positive lung cancers documented a 25% overall response rate to afatinib, a pan-ERBB small molecular tyrosine kinase inhibitor." (PMID 39575425, 2024).
lung cancer (continued). "In lung cancer, the NRG1 fusion has more frequently been observed in the invasive mucinous adenocarcinoma subtype, and in this study, half of the NRG1-positive non-small cell lung cancer cases demonstrated a mucinous histology." (PMID 38173003, 2024). "By applying screening criteria of rec = 5 in the lung cancer group and rec = 9 in the nodule group, while excluding the control group, a total of 2 mutation events (ARHGAP19 and NRG1) were identified." (PMID 39389944, 2024). "In a Korean patient cohort, NRG1 fusion-positive tumors were identified in 0.27% of 8,148 solid tumor cases, with a prevalence of 0.72% in lung cancer patients." (PMID 38957319, 2024). "Seribantumab blocks growth and induces apoptosis in NRG1 fusion models of lung cancer in vitro and in vivo." (PMID 38957319, 2024). "In NRG1 fusion-positive lung cancers, majority of gene partners were identified in upstream regions (84%), and the most common upstream partners were CD74 (41%) and SLC3A2 (20%)." (PMID 37587479, 2023). "A case showed a patient with stage IB NRG1-positive lung cancer expressing significant higher level of NRG1β had an overall survival (OS) of 39 months, which was much shorter than the median OS of patients with stage I NRG1-positive lung cancers." (PMID 37587479, 2023). "The upregulation of NRG1 by ERK3 was confirmed in human lung cancer cell lines H520 and H1229, in which knockdown of ERK3 led to a significant decrease in NRG1 transcript levels." (PMID 34719109, 2022). "It is the authors’ opinion that the mentioned studies highlight the potential clinical importance that NRG1 can have, but acknowledge the limited data and the rareness of its presence in the cancer population, being somewhat specific to lung cancer patients." (PMID 34680187, 2021). "Only 8 common SCNAs were identified in PD patients, including a well-known oncogene NRG1 in non–small cell lung cancer, pancreatic cancer, and invasive mucinous adenocarcinoma." (PMID 34494553, 2021). "Of note, they describe how in patients with wild-type KRAS lung cancer, NRG1 fusions were detected in 11% of patients (4 of 36)." (PMID 34680187, 2021). "The study identified RNASET2, SECISBP2L,NRG1, CHRNA2, OFBC1 and RTEL1 as candidate genes associatedwith lung cancer." (PMID 33959694, 2020). "For example, in a large cohort study of 10,966 Chinese NSCLC patients, the frequency of NRG1 fusions was only 0.16% in these unselected lung cancer patients, with CD74 being the most common fusion partner." (PMID 33505917, 2020). "It has been shown that cancer cells harboring NRG1 fusions overexpress the EGF-like domain of NRG1 III-β3 as a critical step for lung cancer tumorigenesis." (PMID 29515761, 2018). "In the lung cancer cohort, nearly half of the patients (15/36) with NRG1 fusion lung cancer had targets for approved/potential drugs that could be treated with other targeted agents." (PMID 40730881, 2025). "The highest frequency of NRG1 fusions is observed in lung cancer." (PMID 40730881, 2025). "Notably, both CAFs and NFs released more NRG1 than lung cancer cells and normal lung bronchial epithelial cells." (PMID 40959099, 2025). "Interestingly, NRG1 fusion was also detected in cholangiocarcinoma and colorectal carcinoma, besides the well-known breast and lung cancers." (PMID 38173003, 2024). "Similarly, in lung cancer, the SLC3A2-NRG1 fusion gene, often coexistent with KRAS mutations, is subject to ADAM17-mediated cleavage, leading to the release of NRG1." (PMID 38957319, 2024). "Moreover, overexpression of NRG1 has been observed in several cancers, including lung cancer, breast cancer, and pancreatic cancer." (PMID 38957319, 2024). "Also, regarding the importance of SLC3A2-NRG1 fusion in lung cancer, in another study, it was shown that KRAS enhances tumor growth in SLC3A2-NRG1–positive lung cancer cells through ADAM17-mediated NRG1 cleavage." (PMID 38705513, 2024).
lung cancer (continued). "In addition, CD74 can form oncogenic fusion genes with NRG1 to promote the progression of lung cancer cell." (PMID 37745301, 2023). "Several oncogenic fusions protein families exist, with ROS proto-oncogene 1 (ROS1), anaplastic lymphoma kinase (ALK), neurotrophic tyrosine receptor kinase (NTRK), and neuregulin 1 (NRG1) being some of the most common partners that are primarily detected in lung cancers." (PMID 37958963, 2023). "NRG1 was reported to be involved in neural development, regulate diverse biological functions in several types of cells, such as differentiation, proliferation, and apoptosis, and be potentially related to tyrosine kinase inhibitors resistance in lung cancer." (PMID 37424047, 2023). "Moreover, NRG1-fusion genes are potentially actionable genomic events in other cancers such as lung cancer." (PMID 36476658, 2023). "This review highlights how the knowledge of new molecular mechanisms of NRG1 fusion may help in gaining new insights into the molecular status of lung cancer patients and unveil a novel targetable molecular marker." (PMID 34680187, 2021). "This is the largest retrospective study evaluating the clinic-pathological characteristics and outcomes of lung cancer patients harboring NRG1 rearrangements, providing useful information regarding testing methods and responses to convectional therapies as well as afatinib." (PMID 34680187, 2021). "Our finding of a 31% (16/51 cases) prevalence of NRG1 rearrangements in the largest cohort of Caucasian lung IMAs analyzed to date is the first extensive analysis reported and overlaps the prevalence described in Asian lung cancer patients." (PMID 29515761, 2018). "Similarly to the other lung cancer gene fusions, we firstly reported NRG1 rearrangement patterns in form of isolated 3′ signals, thus indicating a strength analogy with ALK and ROS1 fusions, where a 5′ gene deletion was frequently observed." (PMID 29515761, 2018). "The aim of this study was to assess the prevalence of NRG1 rearrangements in a Caucasian population of lung cancer patients, and verify the hypothesis that pErbB3 IHC overexpression is a predictive marker of NRG1 fusions." (PMID 29515761, 2018). "Furthermore, we assessed the clinical significance of NRG1 in lung cancer." (PMID 40959099, 2025). "Furthermore, the effect of NRG1 on lung cancer cell stemness was evaluated." (PMID 40959099, 2025). "Of the eight cases featuring NRG1 fusions, two were lung adenocarcinoma, two were mucinous adenocarcinoma of the lung, two were colorectal adenocarcinoma, one was intrahepatic cholangiocarcinoma, and one was breast invasive carcinoma, thus exhibiting a predominance of lung cancer." (PMID 38173003, 2024). "Research on NRG1 fusion and its signaling mechanism in lung cancer tissues emerged during 2014–2015 alongside studies of adenocarcinoma transcriptome, which demonstrated CD74-NRG1 gene fusion." (PMID 40332427, 2025). "We found that both rhNRG1and CAFs promoted cell proliferation and osimertinib resistance, interestingly, when NRG1 neutralizing antibody was added to CAF-CM, CAF's effect on lung cancer cell proliferation was abrogated." (PMID 40959099, 2025). "NRG1 is a 44 kDa glycoprotein, and ADAM17 is important in the shedding of ligands from lung cancer cells." (PMID 41007372, 2025). "Numerous rare fusions involving receptor tyrosine kinase (RTK) have been detected in lung cancer, including fibroblast growth factor receptor (FGFR), neuregulin 1 (NRG1), and MET Proto-Oncogene, Receptor Tyrosine Kinase (MET)." (PMID 38472960, 2024). "On a therapeutic level, the pan-HER TKI, afatinib, has demonstrated clinical activity in NRG1 rearranged lung cancers with fusions including SDC4-NRG1, SLC3A2-NRG1 and CD74-NRG1." (PMID 38347643, 2024). "Adding NTS to lung cancer cells increases the shedding of TGFα, which activates the EGFR, or neuregulin-1, which activates HER3." (PMID 37508387, 2023).
lung cancer (continued). "For example, the mitochondrial protein TMEM65 is amplified and overexpressed in ~50% of BM from breast and lung cancers, SOX11 is amplified and overexpressed in ~30% of breast and ~80% of lung cancer-BM, and NRG1 is lost and suppressed in ~60% of BCBM." (PMID 28098771, 2017). "Multiple NRG1 fusion partners, including RBPMS, have been found in lung cancer patients." (PMID 36262474, 2022). "Of these fusions, 16 (including ALK, ARAF, BRAF, FGFR1, FGFR3, RET, and ROS1) and 21 (including ABL1, GNAS, JAK2, and NRG1) were classified as either related to lung cancer, or as oncogenes that have not been reported in lung cancer, respectively." (PMID 36153311, 2022). "NRG1 fusions are present in multiple cancer types and in a relative high proportion of lung cancer, specifically IMA, which is one of the most aggressive types of lung cancer." (PMID 34680187, 2021). "Of the 20 largest LVE SNPs, 12 and 4 associate with CVD and smoking/lung cancer, respectively, while only two associate with other cancers (near ZW10 and NRG1; neither in the top 15 LVE SNPs)." (PMID 30642433, 2019). "We analyzed a cohort of 85 formalin-fixed paraffin-embedded (FFPE) IMA and non-IMA lung cancers from Italian patients by combining pErbB3 IHC and NRG1 status assessed by FISH." (PMID 29515761, 2018). "Although subsequent studies have reported NRG1 fusions at low frequencies in various tumor types, NSCLC still exhibits the highest number of cases, and currently, there are no approved targeted therapies specifically designed for NRG1 fusion-positive lung cancers." (PMID 38957319, 2024). "The prognosis for lung cancer patients with the NRG1 fusion protein is not promising." (PMID 36909198, 2023). "In line to this hypothesis, results from pErbB3 immunostaining performed on all 85 FFPE lung cancer samples (51 IMAs and 34 non-IMAs) were correlated with the presence of NRG1 rearrangements assessed by FISH." (PMID 29515761, 2018). "NRG1 fusion occurs mostly in invasive mucinous adenocarcinoma (IMA) and acinar adenocarcinoma subtypes along with non-smoker female lung cancer patients." (PMID 40332427, 2025).
pancreatic cancer (39 papers, 2011 to 2026). "NRG1 fusion is an emerging oncogenic driver, and the FDA has approved drugs for the treatment of non-small cell lung cancer and pancreatic cancer associated with NRG1 fusions." (PMID 40730881, 2025). "A previously unidentified VTCN1/NRG1 fusion was detected which is a known driver fusion event in pancreatic cancer that lacks KRAS driver mutations." (PMID 34504655, 2021). "ErbB3 ligands such as NRG-1 are expressed by pancreatic cancer cells and have been linked to pancreatic cancer cell growth and patient survival." (PMID 21792199, 2011). "The Zeno is now being FDA-reviewed for use in Neuregulin 1 fusion (NRG1+) non-small cell lung cancer (NSCLC) and NRG1+ pancreatic cancers (PDAC)." (PMID 40918454, 2025). "Recently, zenocutuzumab was approved for the treatment of adult patients with advanced unresectable or metastatic non-small cell lung or pancreatic cancer who are positive for NRG1 fusion and who have experienced disease progression despite other treatments." (PMID 40730881, 2025). "For example, 7E3 and YW538.24.71 are antibodies in the preclinical stage directed to the NRG1 IgG-like domain that blocks NRG1-dependent growth in pancreatic cancer models." (PMID 40243603, 2025). "Data have been presented on zenocutuzumab, an inhibitor of human epidermal growth factor receptor 2 (HER2) and 3 (HER3), which has shown promising efficacy in patients with pancreatic cancer carrying the fusion in the neuregulin 1 (NRG1) gene." (PMID 38329611, 2024). "Although NRG1 gene rearrangement is uncommon in pancreatic cancer, it tends to be enriched in younger patients with KRAS wild-type pancreatic cancer." (PMID 38627681, 2024). "Cancer associated fibroblasts secrete neuregulin-1 (NRG1), which activates the HER3 pathway and promotes pancreatic tumor growth in vivo." (PMID 37880707, 2023). "NRG-1 fusions are noted in <1% cases of pancreatic cancer and clinical studies have shown efficacy with a drug called zenocutuzumab." (PMID 37366887, 2023). "For example, 7E3 is an antibody directed to NRG1 IgG-like domain that blocks NRG1-dependent growth in pancreatic cancer models." (PMID 36271429, 2022). "The discovery of recurrent fusions involving NRG1 in KRAS wild-type pancreatic tumors, as well as case reports of fusions involving BRAF, PRKACA, NTRK1/3, and RET, prompted us to systematically screen for fusion genes in this cancer entity." (PMID 33441414, 2021). "An on-going phase I/II trial using zenocutuzumab (HER2/HER3 inhibitor), has already enrolled 250 pancreatic cancer patients harbouring neuregulin-1 (NRG1) gene fusion (NCT02912949)." (PMID 33546207, 2021). "Another phase I/II study is studying single-agent zenocutuzumab (MCLA-128) in patients with solid tumors, including NSCLC and pancreatic cancer, harboring an NRG1 fusion." (PMID 34680187, 2021). "Sequencing of a new metastatic lesion using GEM ExTra® revealed a VTCN1/NRG1 oncogenic fusion that is most likely the driver event of the pancreatic cancer." (PMID 34504655, 2021). "7E3, an original antibody to NRG1 promotes antibody dependent cellular toxicity in NRG-1+ pancreatic cancer cells and CAFs." (PMID 32466266, 2020). "Pertuzumab efficacy in pancreatic cancer cells was greatly increased when exogenous NRG1 was added as stimulator, thus demonstrating that ligand-induced HER2/HER3 dimers strongly affect the fate of pancreatic tumor cells." (PMID 25216528, 2014). "By analogy, and given the presence of EGFR-ErbB3 heterodimers in pancreatic cancer cells, we postulated that NRG-1, a specific ErbB3 ligand, is secreted by the stroma, forms an active paracrine loop and influences response to EGFR inhibition by erlotinib." (PMID 21792199, 2011). "More importantly, aberrant pancreatic cancer ErbB3 signalling is a ligand-driven mechanism supported by CAF from the surrounding stroma as a source of NRG-1." (PMID 21792199, 2011).